PLN (phospholamban)
Diseases named in the same sentence as PLN in open-access papers (continued):
Sharing a sentence is not in itself a finding about the gene and the disease.
heart failure (continued). "There is broad precedent for this general concept, however, as CaMKII mediated RyR2 phosphorylation and PKA mediated phospholamban phosphorylation have established roles in the development of heart failure." (PMID 30520731, 2018). "As such, ablation of Phospholamban has subsequently been used as an experimental approach to improve cardiac function in rodent models of heart failure." (PMID 29119312, 2017). "The diminished SR Ca2+ cycling through inappropriate interactions between PLN and SERCA2a attenuates the progression to heart failure." (PMID 29068413, 2017). "A causative role for PLN R9C in DCM is evidenced by co-segregation in a large 4 generation family affected by DCM and heart failure." (PMID 29119312, 2017). "The missense mutation at PLN residue 9 (PLN-R9C) has been reported to cause inherited DCM and heart failure in patients." (PMID 28102477, 2017). "This study emphasised a clear contrast between the disease phenotypes in human and rodents since ablation of PLN in mice seemed to be beneficial in the setting of heart failure, whereas human carriers of PLN-L39stop develop severe and lethal cardiomyopathies." (PMID 28102477, 2017). "Characterisation of those PLN mutations generally revealed disruption of intracellular calcium handling, precipitating clinical manifestations of ACM, DCM and heart failure." (PMID 28102477, 2017). "Transgenic mice carrying the deletion of arginine 14 in Phospholamban die between 2 and 16 weeks of age due to ventricular dilatation and heart failure." (PMID 29119312, 2017). "Sarcoplasmic reticulum Ca2+-ATPase 2a (SERCA2a) and its inhibitory protein called phospholamban (PLN) are pivotal for Ca2+ handling in cardiomyocyte and are known that their expression level and activity were changed in the heart failure patients." (PMID 27992596, 2016). "Mutations in the phospholamban (PLN) gene are associated with dilated cardiomyopathy (DCM) and severe heart failure." (PMID 26917049, 2016). "Accordingly, inactivation of TRα1 receptor preventing the reactive hypertrophy following myocardial infarction results in heart failure with increased phospholamban (PLB) expression and marked activation of p38MAPK." (PMID 26124827, 2015). "Accordingly, inactivation of TRα1 receptor prevents reactive hypertrophy after myocardial infarction and results in heart failure with increased phospholamban (PLB) expression and marked activation of p38MAPK." (PMID 24683435, 2014). "Angiotensin II type 1 receptor is a key component of the pathogenesis of heart failure, and gene inactivation of phospholamban has been shown to enhance basal cardiac contractility." (PMID 24781449, 2014). "An emerging pathway in modulating PLN activity is inhibition of protein phosphatase 1 (PP1) that is significantly elevated in heart failure." (PMID 24312496, 2013). "A decrease in the level of PLN phosphorylation at Ser16 (mainly affected by PKA activity) has been reported in some papers in heart failure, as against decreased levels of Thr17 phosphorylation (affected by the decreased CaMKII activity)." (PMID 19125184, 2009). "The phospholamban (PLN) R14del mutation is a pathogenic variant linked to inherited cardiomyopathy, which contributes to the development of dilated cardiomyopathy (DCM) and heart failure." (PMID 40552689, 2025). "Since a low SERCA2a/PLN ratio may contribute to heart failure, we also measured the ratio in this study." (PMID 40905134, 2025). "Standard heart failure therapy involving eplerenone or metoprolol was shown to be ineffective in PLN-Arg14del heterozygous mice, underscoring the need for the development of novel therapeutic strategies targeting PLN-Arg14del." (PMID 40556736, 2025). "The enhanced lusitropic and inotropic effects, resulting from PLN absence/dysfunction, might explain the observed DCM, complicated by heart failure, and HCM phenotypes in PLN mutation carriers." (PMID 39273332, 2024).
heart failure (continued). "ASOs are specifically designed to target PLN mRNA, downregulating PLN activity and its interaction with SERCA2a in heart failure murine models, preventing left ventricular dilatation, improving left ventricular contractility, and leading to an increase in survival rate." (PMID 39684857, 2024). "Diminished activity of the cardiac SERCA2a isoform in heart failure (HF), often accompanied by increased phospholamban (PLB)/SERCA ratio and/or decreased PLB phosphorylation, results in slower and less complete relaxation after each beat, elevated diastolic Ca2+, and degraded cardiac function." (PMID 36551215, 2022). "Due to this, SERCA2a overexpression may still be of benefit in PLN R14del or even general heart failure and should therefore be studied when it is known how to effectively deliver genes to the heart." (PMID 35699837, 2022). "Several disease variants in the PLN gene have been described in heart failure, but no specific therapies exist beyond standard heart failure treatments or heart transplantation." (PMID 35853412, 2022). "Moreover, a single systemic administration of antisense ODNs targeting phospholamban, a SERCA2a inhibitor, dramatically improved contractility in a pressure overload model of heart failure." (PMID 34089101, 2021). "There remains controversy as to whether the regulation of SERCA activity is altered in human myocardium from patients with heart failure or whether decreased SERCA activity is due to changes in SERCA or phospholamban expression." (PMID 34299010, 2021). "From these observations, it was concluded that the impaired SR function in human heart failure might be due to reduced cAMP-dependent phosphorylation of phospholamban resulting in a difference in SERCA activity." (PMID 34299010, 2021). "Administration of standard heart failure therapy did not rescue the phenotype, underscoring the need for better understanding of the pathophysiology of PLN-R14del-associated cardiomyopathy." (PMID 32555305, 2020). "Thus, PLN-R9C has the potential of serving as an early stage biomarker for cardiomyopathy and subsequent heart failure." (PMID 33265898, 2020). "Conversely, other groups found that decreased inhibition of SERCA2a through increased PLN phosphorylation might exaggerate heart failure and arrhythmogenic activity." (PMID 30986276, 2019). "The mechanism by which CCM provides benefit can be seen at the cellular level where improved calcium handling (phosphorylation of phospholamban, upregulation of SERCA-2A), reversal of the fetal myocyte gene program associated with heart failure, and reverse remodeling are observed." (PMID 27394714, 2016). "While CSQ overexpression causes severe heart failure symptoms and premature death, a significant ameliorating effect on survival rate was observed in PLN homozygous KO/CSQ-Tg mice compared to PLN wild type/CSQ-Tg mice (median survival days are 55 and 50 days, respectively)." (PMID 27992596, 2016). "ACE-I prevents downregulation of SERCA2a and phospholamban protein expression in heart failure." (PMID 22853195, 2012). "Human carriers of the PLN-R14del variant exhibit highly variable phenotypes, ranging from asymptomatic to cardiomyopathic with clinical features of both ACM and DCM that may progress to heart failure and SCD." (PMID 37144056, 2023). "Indeed, decreased PLN phosphorylation, leading to a decrease of Ca2+ uptake by SERCA2a, is a central feature of heart failure, and decreased inhibition of SERCA2a by PLN ablation can prevent progression of heart failure." (PMID 30986276, 2019). "Importantly, changes in MG23 expression in H9C2 cells after hypoxia are comparable with the reported changes in protein expression of key Ca2+-regulatory proteins including SERCA, phospholamban, and the sarcolemmal Na+/Ca2+ exchanger that occur in heart failure (57, –, 59)." (PMID 28630041, 2017).
heart failure (continued). "PLN inhibition and SERCA2a activation are known to show beneficial effects on cardiac function and hypertrophy in various HF models, and increase contractility in the cardiomyocytes isolated from heart failure patients, although there are few reports with respect to improvement of HF mortality." (PMID 27992596, 2016). "Although a decrease in SERCA2a has been described as a hallmark in cardiac failure, we could not find any difference in either SERCA2a, PLN expression, the SERCA2a/PLN ratio or the estimated activity of SERCA2a in SHRF when compared to W of the same age." (PMID 24781001, 2014). "Because cardiac dysfunction observed in cardiomyopathy and heart failure is strongly associated with the expression profile of the cardiac proteins related to intracellular calcium handling, we evaluated the SERCA2, PLN, phospho-ser16-PLN, phospho-thr17-PLN, PP1, and NCX." (PMID 21470409, 2011). "It interferes with PKA-mediated PLN phosphorylation and consequently disrupts the regulatory function of PLN resulting in sustained SERCA2 inhibition, development of DCM, heart failure and premature death." (PMID 40556736, 2025). "Specifically, EETs can maintain Ca2+ homeostasis in myocardial cells and alleviate the symptoms of heart failure in rats by upregulating the expression of sarcoplasmic reticulum Ca2+-ATPase (SERCA) and phospholamban (PLB)." (PMID 33488937, 2020). "During end‐stage heart failure, there is a decrease in SERCA2 activity due to a decrease in SERCA2 expression and an increased inhibitory effect of PLN on SERCA2." (PMID 31325238, 2019). "In AF compounded by heart failure, decreased SERCA2 and phosphorylated PLN, and increased NCX1 expression were observed." (PMID 30896405, 2019). "In general, dysfunctional PLN highly disrupts the cardiac intracellular calcium handling, finally ending in hypertrophy, DCM, ventricular arrhythmias, heart failure and premature death." (PMID 28102477, 2017). "In heart failure, PP2A dephosphorylates phospholamban (PLN), which reduces sarcoplasmic reticulum (SR) Ca2+ ATPase (SERCA2a) activity, SR Ca2+ uptake, and SR Ca2+ loading." (PMID 24465463, 2014). "In contrast, by using gene features, our posterior distributions of shet indicate that PLN is strongly constrained but TBC1D3 is not, consistent with the observation that heterozygous LOFs in PLN cause severe cardiac dilation and heart failure." (PMID 37398424, 2023). "A more recent study claims that there is little evidence of phospholamban down-regulation in heart failure." (PMID 35741007, 2022). "For example, the scientific literature has reports that phospholamban changes during heart failure and other reports where it does not." (PMID 35741007, 2022). "Thus, in heart failure, there is increased expression of BNP and the sodium–calcium exchanger, with decreased expression of SERCA2A, alpha-MHC, and phospholamban." (PMID 27394714, 2016). "With regard to the therapeutic target for heart failure, we chose PP1β, the PP1 isoform of which we previously reported that it dominantly suppresses SR-mediated Ca2+ uptake via PLN dephosphorylation, and its expression has been reported to be upregulated in failing hearts." (PMID 22558250, 2012). "Our data do not support a role for the PLN -36A>C alteration in modulating the heart failure phenotype, including its clinical course, in humans." (PMID 19638213, 2009). "Taken together, our data do not support a role for the PLN -36A>C alteration in modulating the phenotype or clinical course of heart failure." (PMID 19638213, 2009). "PLN-Arg14del has only been found in the heterozygous state, with patients exhibiting a spectrum of highly variable phenotypes that range from asymptomatic to ACM or DCM that may progress to heart failure or sudden cardiac death." (PMID 40556736, 2025).
heart failure (continued). "The PLN-R9C mutant heart has a calcium flux imbalance due to the mutant (R9C) form of phospholamban which constitutively inhibits the SERCA ATPase responsible for calcium ion transport from the cytosol into the sarcoplasmic reticulum in muscle 22, which eventually leads to heart failure." (PMID 20127684, 2010). "Second, in heart failure, it is well established that SERCA levels are reduced, but there is often either no change or a slight increase in PLN expression which would dramatically increase the PLN to SERCA ratio." (PMID 30299255, 2018).
cardiomyopathy (89 papers, 2010 to 2026). A disease of the heart muscle or myocardium proper. "The phospholamban (PLN) R14del mutation is associated with cardiomyopathies, making it a crucial target for precise gene‐editing strategies." (PMID 40552689, 2025). "A second uncertain variant c.35T>C (p.Ile12Thr), in the PLN gene, linked to cardiomyopathies, was also detected in the proband (ClinVar NCBI)." (PMID 41287789, 2025). "The fact that PLN variants lead to multiple forms of cardiomyopathies, along with the various clinical manifestations associated with single variants, such as Arg14del, Arg25Cys and Leu39Ter, suggest the absence of a clear genotype-phenotype correlation." (PMID 40556736, 2025). "Phospholamban (PLN) p.Arg14del (R14del, R14∆/+) is the most commonly identified pathogenic variant that causes cardiomyopathy in the Netherlands." (PMID 40048085, 2025). "The PLN Foundation, established in 2012, supports about 1700 individuals with a phospholamban (PLN) gene mutation causing severe cardiomyopathy." (PMID 40338481, 2025). "PLN p.Leu39* variant-driven cardiomyopathy presented mostly as hypertrophic, with frequent progression to end-stage dilated HCM." (PMID 38392255, 2024). "In terms of the genetic background, one patient had a history of von Hippel–Lindau disease and another patient had a history of inherited cardiomyopathy associated with a mutation in the phospholamban gene." (PMID 38398340, 2024). "In a second disease modeling application we utilized CASAAV-HDR to precisely delete arginine 14 of PLN - another mutation found in human cardiomyopathy patients." (PMID 39677651, 2024). "Mutations in the human phospholamban (PLN) gene are linked to familial forms of cardiomyopathy, including arrhythmias, ventricular dilation, and possible sudden cardiac death." (PMID 38785523, 2024). "A phospholamban gene variant was reported to alter proteostasis, elevating phospholamban aggregation and predisposing to cardiomyopathy." (PMID 37922111, 2024). "Next, we utilized CASAAV-HDR to create another mutation associated with human cardiomyopathy, arginine 14 deletion (R14Del) within the N-terminus of Phospholamban (PLN)." (PMID 39677651, 2024). "We assessed the localization of PLN-R14Del and quantified cardiomyocyte phenotypes associated with cardiomyopathy, including cell morphology, activation of PLN via phosphorylation, and calcium handling." (PMID 39677651, 2024). "In particular, the homozygous model with insertion of the mouse mutant PLN exhibited cardiac dilatation, contractile dysfunction, cardiac fibrosis, high susceptibility to arrhythmias, cardiomyopathy and early mortality." (PMID 37144056, 2023). "The present study aimed to demonstrate that human R14del-PLN is associated with myofilament dysfunction, potentially one of the underlying cellular mechanisms contributing to the pathogenesis of cardiomyopathy." (PMID 36768995, 2023). "Strikingly, in the Netherlands the PLN-R14del genetic variant is the most prevalent cardiomyopathy-related mutation (>1,500 carriers), present in ∼12% of patients with ACM and ∼15% of patients with DCM." (PMID 37144056, 2023). "Phospholamban (PLN) is a major regulator of cardiac contractility, and human mutations in this gene give rise to inherited cardiomyopathies." (PMID 36768995, 2023). "Mutations in the PLN gene are responsible for a severe cardiac phenotype with an arrhythmogenic, as well as dilated, cardiomyopathy associated with a severe prognosis and high mortality." (PMID 37408239, 2023). "Since protein aggregation is a well-known pathogenic hallmark of many diseases and in aging, PLN protein aggregation has been implicated as a potential mechanism driving cardiac remodeling in PLN-R14del cardiomyopathy." (PMID 35269571, 2022). "In this way, gene silencing of PLN is known to possess beneficial properties in both PLN r14del as well as general HF, allowing it to be a promising treatment strategy for PLN r14del-associated cardiomyopathy and HF." (PMID 35699837, 2022).